NLRP3 (NLR family pyrin domain containing 3)
Diseases named in the same sentence as NLRP3 in open-access papers (continued):
Sharing a sentence is not in itself a finding about the gene and the disease.
infection (continued). "Thus, we observed cleavage of NLRP3 after infection with Leishmania." (PMID 26114647, 2015). "The aim of this study was to determine whether the activation of NLRP3 inflammasome depends on infection with the periodontal pathogen Porphyromonas gingivalis (P. gingivalis), or stimulation with P. gingivalis lipopolysaccharide (LPS), and/or extracellular adenosine triphosphate (ATP)." (PMID 26511096, 2015). "For B. pseudomallei, it has been suggested, that the NLRC4 inflammasome responds to T3SS3 deployment, which takes place early in the infection cycle, whereas activation of the NLRP3 inflammasome might require escape from the phagosome, which probably occurs later." (PMID 24626296, 2014). "Because NLRP3 activation leads to caspase-1 activation and consequent IL-1β secretion, we next asked whether caspase-1 and IL-1β are required for NLRP3-dependent NO production in response to T. cruzi infection, and what role these molecules play in the control of infection by macrophages." (PMID 24098823, 2013). "Finally, H. influenzae infection induces NLRP3 expression and activation in human lung tissue, which might be a mechanism of infection-triggered COPD exacerbations." (PMID 24312100, 2013). "Notably, the difference in the amastigotes numbers of the macrophages derived from the knockouts and the WT mice was not related to the invasion rate of T. cruzi, as similar numbers of amastigotes were observed in the macrophages from WT, NLRP3−/− and caspase-1−/− mice after 2 h of infection." (PMID 24098823, 2013). "However, IL-1α release and cell death following infection with flagellin-deficient L. pneumophila are independent of NLRP3, indicating that caspase-11 also mediates an NLRP3-independent response towards flagellin-deficient L. pneumophila." (PMID 23762026, 2013). "Also, the conversion of LC3-I to LC3-II was induced upon infection with ΔtdhAS but not with ΔtdhASΔvopQ, suggesting that VopQ-dependent autophagy is induced in both wild-type and NLRP3-deficient BMMs." (PMID 23357873, 2013). "Next, we tested whether viral RNAs were able to activate the NLRP3 inflammasome after infection." (PMID 22916014, 2012). "Therefore, NLRP3 appears to play a particularly important role in infection with PLY-expressing S. pneumoniae, although the data with PLN-A suggest that even in the absence of PLY, NLRP3 may play a role in protective immunity." (PMID 21085613, 2010). "IRF1 also regulates the expression of key components necessary for NLRP3 and AIM2 activation after infection, including ZBP1 and guanylate-binding proteins." (PMID 40018047, 2025). "However, upon infection of cells that express the NLRP3 inflammasome, (e.g., macrophages), with pathogens that activate this pathway (e.g., Listeria monocytogenes), TBK1/IKKε-deficient cells die rapidly, prematurely, and exclusively by enhanced NLRP3-driven pyroptosis." (PMID 40053580, 2025). "Among these macrophages, the percentages of NLRP3 and IL1β positive cells were significantly higher during HN878‐infection, compared with CDC1551 infection." (PMID 41287823, 2025). "In this study, we found that in the infection model of THP-1 derived human macrophages, which express multiple inflammasomes, E. tarda induced pyroptosis in a manner that depended on NLRC4, NLRP3, ASC, Casp1, and Casp4." (PMID 39951384, 2025). "Even infection with the RIPK1-activating pathogen, Yersinia pseudotuberculosis, results in enhanced RIPK1–caspase-8 activation and enhanced secondary NLRP3 activation." (PMID 40053580, 2025). "Consistently, confocal microscopy results revealed that upon PRV and EMCV infection, the TGN disassembled from a single perinuclear cluster into dTGN, where NLRP3 accumulated." (PMID 39869629, 2025).
infection (continued). "Consistently, G. parasuis infection significantly up-regulated NLRP3, GSDMD, and caspase-1 expression at 24 h post-infection (hpi), indicating activation of the canonical pyroptotic pathway in PAMs." (PMID 40665414, 2025). "Co-staining of NLRP3 with the IBV nucleocapsid (N) protein, a marker of productive infection, revealed a striking redistribution of NLRP3 from a diffuse cytoplasmic pattern in uninfected cells to concentrated perinuclear puncta in IBV-N-positive cells." (PMID 41334910, 2025). "Confocal immunofluorescence, coimmunoprecipitation, and western blot all confirmed that the non‐structural (NS) viral protein colocalized with NLRP3 when overexpressed and following SFTSV infection." (PMID 39878363, 2025). "Composed of the sensor protein NLRP3, the adaptor protein ASC, and pro-caspase-1, it recognizes cellular damage and infections, triggering the release of pro-inflammatory cytokines like IL-1β and IL-18, and inducing pyroptosis." (PMID 40688353, 2025). "In this review, we focus specifically on how maternal immune activation (MIA) — induced by infections, autoimmune diseases, or other immune challenges during pregnancy — affects fetal brain development via the P2X7/NLRP3/IL-1β signalling axis." (PMID 40713568, 2025). "To evaluate the mechanism through which N. caninum infection regulates IL-1β, we tested MCC950 (an NLRP3 inhibitor), VX765 (a CASP1 inhibitor), and SN-50 (an NF-κB inhibitor) in THP-1 cells following infection with parental strain Nc1 and NcGRA7KO." (PMID 41357231, 2025). "While an early inflammatory response triggered by NLRP3 activation is protective against IAV, inflammasome activation in the later stages of infection contributes to disease pathogenesis and mortality." (PMID 41011440, 2025). "Experimental data show that CEK cells activate the NLRP3 inflammasome upon IBV infection, suggesting that renal epithelial cells are both targets of infection and active contributors to inflammation." (PMID 41334910, 2025). "This conclusion was further supported by data from Nlrp3–/– MEFs, which exhibited levels of cell death similar to those of WT controls following MPXV infection." (PMID 41225161, 2025). "NLRP1, NLRP3, AIM2, and IFI16 inflammasome sensors regulate infection-induced caspase-1 activation and cleavage, allowing caspase-1-dependent pyroptosis." (PMID 40593504, 2025). "Consequently, these results demonstrated that NLRP3 might drive CV-A16 and CV-A10 infection." (PMID 38705479, 2024). "Upon infection with HSV-1 or cytosolic DNA stimulation, STING engages with NLRP3, facilitating inflammasome activation via dual mechanisms." (PMID 38426093, 2024). "Here, we observed higher TLR2, TLR4, TLR5, TLR6, TLR8, TLR9, Myd88, NLRP3, ASC, and TNF-α mRNA expression at seven weeks after infection by S. mansoni in BALB/c and C57BL/6 mice compared to Swiss mice." (PMID 38896633, 2024). "Since NLRP3-dependent pyroptosis is executed by GSDMD, we also depleted GSDMD to verify its role in RVFV-infection induced IL-1β release." (PMID 39213434, 2024). "Oral zinc supplementation during infection supports the NLRP3-ASC-Caspase-1 pyroptotic axis, while zinc gluconate exposure also seems to upregulate NLRP3 and pyroptosis." (PMID 39097717, 2024). "NLRP3 inflammasome contains NLRP3, ASC, and caspase-1, which induces cell death and inflammation by responding to infection and stress." (PMID 38467635, 2024). "Although the crosstalk between type I IFN and inflammasomes in response to infection is somewhat established, little is known about how type I IFN and the NLRP3 inflammasome interact in the context of sterile inflammation and autoinflammatory disease." (PMID 38527803, 2024). "Extracellular ATP not only attracts immune cells to the site of infection but also activates the P2X7 receptor, further promoting NLRP3 inflammasome activation and creating a positive feedback loop." (PMID 39735183, 2024).
infection (continued). "NLRP3 acts as a crucial innate immune defence molecule, with its activation providing protective effects in ALD mice following infection." (PMID 39605303, 2024). "Immunohistochemical staining revealed that the NLRP3 and GSDMD protein expression was elevated significantly (p < 0.01) in the infection group in contrast to the control group." (PMID 38515339, 2024). "When macrophages were infected with a high dose of DENV-1 (MOI = 1), NLRP3 and GSDMD mRNA reached a peak value in the early stage of infection (h.p.i = 24 h), while the Caspase-1 mRNA level gradually increased with the infection time." (PMID 39767659, 2024). "In the course of acute infection, two essential components for inflammasome formation, namely the DNA sensor IFI16 and NLRP3, are triggered in bovine kidney cells." (PMID 38590522, 2024). "During IAV (Influenza A virus) infection, the cell death regulator MLKL facilitates potassium ion efflux, partially activating the NLRP3 inflammasome." (PMID 39735183, 2024). "Human monocyte-derived macrophages expressed NLRP3 and infection with SARS-CoV-2 induced cleavage of IL-1 and GSDMD within eight hours post infection." (PMID 38664396, 2024). "Among them, miR-223-3p, who had a specific binding site with NLRP3 3’UTR, was the most important gene closely related to inflammation and infection." (PMID 38448875, 2024). "RVFV infection of the Nlrp3-/- mouse model demonstrated that the RVFV-triggered NLRP3 pyroptosis contributed to RVFV inflammatory pathogenesis and fatal infection in vivo." (PMID 39213434, 2024). "However, the infection mechanism has not been extensively reported, and the relationship between this susceptibility and the protective effect of NLRP3 on intestinal permeability remains unclear." (PMID 39605303, 2024). "To evaluate mice mortality during disease development, we monitored mice for up to 14 days after infection and found that SARS-CoV-2-infected Nlrp3-/- were significantly more resistant to death as compared to Nlrp3+/+ controls." (PMID 38838044, 2024). "The host detects pathogen invasion through cytosolic PRRs such as NLRP3, AIM2, and NLRC4, and induces immune responses to resistant infection through the inflammasome assembly." (PMID 38136879, 2023). "Another report suggests that infection induces neutrophils pyroptosis via ATP-mediated P2X7R signaling, resulting in cytoplasmic low K+ activation of NLRP3 inflammasome together with mature IL-1β and IL-18 release." (PMID 37063905, 2023). "Together, NLRP3 inflammasome activation and its downstream effectors GSDMD, IL-1β and IL-18, shelter against potential infections and help to maintain intestinal homeostasis." (PMID 37891577, 2023). "In the current study, we characterized the relative contributions of T3SS, the NLRP3 versus the NLRC4 inflammasomes, and GSDMD and GSDME to IL-1β release and pyroptosis in neutrophils versus macrophages following infection with P. aeruginosa." (PMID 37730693, 2023). "The inflammasome molecules AIM2, NLRP3, NLRP6 and NLR Family Apoptosis Inhibitory Protein (NAIP)/NLRC4 were reported to play important roles in epithelial cells by protecting against infection and maintaining tissue homoeostasis." (PMID 37365163, 2023). "In WT macrophages, we observed PI incorporation after 4 h infection and this early cell permeabilization was GSDMD and Caspase-1/11-dependent and NLRP3 independent, suggesting that GSDMD cleavage occurs upstream to the NLRP3 inflammasome activation." (PMID 36828815, 2023). "Firstly, we detected the expression of NLRP3 and ASC in lung tissues on day 3 post-infection by immunofluorescence staining." (PMID 37704783, 2023). "Several Leishmania spp., including L. amazonensis, L. major, L. braziliensis and L. infantum chagasi, activate NLRP3- and ASC-dependent caspase-1 in macrophage cells, and the infection of Leishmania spp." (PMID 36869360, 2023). "Infection of macrophages with IAV triggers the release of ox-mtDNA and activation of NLRP3 and AIM2 inflammasomes." (PMID 37001140, 2023).
infection (continued). "Upon damage or infection, intracellular MIF can also interact with nitrogen permease regulator-like 3 (NLRP3) to facilitate the interaction between NLRP3 and vimentin, resulting in the release of IL1β." (PMID 38052787, 2023). "Infection with HSV1 or F. novicida can induce AIM2-dependent and NLRP3/NLRC4-independent activation of CASP1, followed by the release of IL-1β and IL-18 and cell death." (PMID 36845112, 2023). "The immunofluorescence staining results showed that RACK1, NLRP3 and NEK7 were diffusely distributed in the cytoplasm in uninfected cells, while PmCQ2 infection induced the colocalization of RACK1 with NLRP3 and NEK7 (white arrows)." (PMID 37684678, 2023). "Infection boosted IL-1β, IL6 and NLRP3 levels in TLR7 expressing AMФ but these proinflammatory markers were suppressed upon TLR7 deficiency." (PMID 37795093, 2023). "In this review, we will focus on the NLRP3, NLRP6, NLRC4 and AIM2 inflammasomes and how they are activated and regulated during infections with Gram-positive bacteria, including Staphylococcus spp., Streptococcus spp." (PMID 36761775, 2023). "At the same time, Nlrp3, Caspase-1, and GSDMD-N significantly increased after infection with PEDV, while GSDMD significantly decreased." (PMID 38132483, 2023). "As a second approach to examine the role of NLRP3, neutrophils from C57BL/6 mice were incubated with the well-characterized, highly specific NLRP3 inhibitor MCC95033 prior to infection with P. aeruginosa." (PMID 37730693, 2023). "In agreement, WT Caco-2 cells pretreated with a chemical inhibitor of the NLRP3 inflammasome, MCC950, underwent comparable levels of inflammasome activation in response to Δ6 Yptb infection as infected vehicle control-treated Caco-2 cells." (PMID 37615436, 2023). "NLRP3 expression and ASC and caspase‐1 are needed to cleave pro caspase‐1 to secrete mature IL‐1β following IV infection." (PMID 37773712, 2023). "To determine the impact of Ch25h on AM-specific NLRP3 inflammasome signaling, we isolated AMs from PBS and S. pneumoniae instilled lung and assessed gene expression at select time points of infection." (PMID 36831236, 2023). "Newer studies suggest that post-LRV infection, TLR3-driven inflammasome-independent cytokine production can incite autophagy, leading to ATG5-mediated degradation of NLRP3 and ASC." (PMID 37892135, 2023). "NLRP3 inflammasome activators like ATP, nigericin, and MSU crystals were employed to replace SE infection." (PMID 37155697, 2023). "Mice that received JWH133 treatment had significantly lower levels of NLRP3, ASC, and reduced caspase-1 activation at 24 h after PA infection." (PMID 36463179, 2022). "In canonical pathway, inflammasomes such as NLRP3, NLRP4 and AIM2 are responsible for recognizing extracellular pathogens infection and then activate the caspase-1, which cleaves GSDMD into the N-terminus and C-terminus fragments later." (PMID 35573789, 2022). "In late-stage infections, caspase-11 plays a predominate role in initiating pyroptosis through cleavage of GSDMD in addition to NLRP3 activation." (PMID 35626718, 2022). "P. aeruginosa strain PAO1 infection is able to activate NLRC4 and NLRP3 inflammasomes and initiate a type of rapid inflammatory cell death termed pyroptosis in macrophages." (PMID 36604139, 2022). "The diverse array of DNA viruses activates cytosolic pattern recognition inflammasome receptors (NLRP3 and AIM2) during the infections." (PMID 35806033, 2022). "Rather, we found that infection of human macrophages with Salmonella grown under SPI-1-inducing conditions activates multiple inflammasomes, including NAIP/NLRC4, CASP4/5, and NLRP3." (PMID 35073381, 2022). "Using these models, they showed that inflammasome pathway components (NLRP3, ASC, AIM2, and caspase-1) are induced upon infection of bone marrow-derived macrophages." (PMID 36298668, 2022).
infection (continued). "The data show that IL-1β maturation as well as caspase 1 cleavage is abrogated in the NLRP3 knockdown PAMs, suggesting that inflammasome activation induced by ASFV-H240R infection depends on NLRP3." (PMID 36326277, 2022). "The NLRP3, GSDM-D, and caspase-3 KO cell lines showed a decrease of both extracellular and intracellular titre upon infection compared to wild-type cells, indicating that programmed cell death is necessary for efficient HCV propagation." (PMID 35237259, 2022). "Together, our findings demonstrate a mechanism by which ECHO 11 induces inflammatory responses by activating NLRP3 inflammasome, providing novel insights into the pathogenesis of ECHO 11 infection." (PMID 36026486, 2022). "NLRP3 is known to recognize IAV infection and to mediate a host response that assists in clearing infection and aids in protection." (PMID 35062292, 2022). "Infection performed in NOD-, LRR-, and pyrin domain-containing three (NLRP3) knockdown cells indicated that NLRP3 is essential for SVA-induced IL-1β secretion." (PMID 35254168, 2022). "The NLRP3 inflammasome, which contains the NOD-like receptor NLRP3, the adaptor ASC, and the effector caspase-1, is the most studied and best characterized inflammasome regarding infection and in chronic inflammatory diseases." (PMID 36145246, 2022). "Two NLRs, NLRP3 (LRR and pyrin domain-containing 3) and NLRC4 (NOD-, LRR- and CARD-containing 4) can sense the infection of S. Typhimurium, which cooperatively orchestrates the protective innate immune response." (PMID 35604097, 2022). "Another study described that infection with mycobacterium tuberculosis up-regulated the expression of MFN2 and promoted the assembly and activation of the NLRP3 inflammasome." (PMID 35250595, 2022). "CB2R activation reduced the NF-κB and NLRP3 inflammasome activation, whilst genetic deletion of CB2R enhanced the NLRP3 activation post-PA infection." (PMID 36463179, 2022). "NLRP3 and NLRC4 are two of the key inflammasomes that are of importance during infection with Salmonella." (PMID 34864057, 2022). "Infection of Casp-1 inhibitor-treated cells and NOD-, LRR- and pyrin domain-containing 3 (NLRP3)-knockdown cells indicated that NLRP3 is essential for FMDV-induced IL-1β secretion." (PMID 35062226, 2021). "Altogether, the results indicate that NLRP3 and ASC are required for enhanced production of IL-1β and increased cell death during ΔpknF mutant infection." (PMID 34324582, 2021). "Since we demonstrated that NLRP3, ASC, and IRGM are key regulators for the Golgi shape in homeostasis or infection with HCV, we then examined their regulation upon induction of the components of the inflammasome by a virus-unrelated activator, using nigericin." (PMID 33208442, 2021). "Macrophages infected with B. thailandensis undergo NLRP3-, NLRC4-, caspase-1-, caspase-11-, and GSDMD-dependent pyroptosis (52, –, 60), but the role of other cell death pathways during infection is poorly understood." (PMID 34154417, 2021). "The relative expression of NLRP3, ASC and caspase-1 mRNA was generally upregulated first and then downregulated in the infection groups." (PMID 33678162, 2021). "We found the expressions of mRNA expression of caspase-1, GSDMD, caspase-3, MLKL, RIPK3, NLRP3, IL-1β and IL-18 and of proteins cleaved caspase-1, GSDMD, cleaved caspase-3 and pMIKL in the macrophages of the three infection groups to be upregulated (P<0.05)." (PMID 34513732, 2021). "These genes regulate a wide range of functions during infection, such as activation of chemokine production, RNS silencing suppression, NLRP3 inflammasome activation, etc.." (PMID 33572725, 2021). "The green fluorescence intensity of NLRP3 and ASC was higher after infection with P. bovis or P. ciferrii compared to the control." (PMID 34895324, 2021).